RN7SL340P (RNA, 7SL, cytoplasmic 340, pseudogene)
Gene: Miscellaneous RNA gene on chromosome 19 (29,233,090 to 29,233,385, reverse strand). Ensembl gene ENSG00000241604.
Homologues: Orthologues: chimpanzee Metazoa_SRP (98% identical), macaque Metazoa_SRP (91% identical). Paralogues in human: RN7SL2 (81% identical), RN7SL1 (81% identical), RN7SL3 (79% identical), RN7SL63P (79% identical), RN7SL386P (78% identical), RN7SL147P (78% identical), RN7SL186P (78% identical), RN7SL650P (78% identical), RN7SL679P (77% identical), RN7SL126P (77% identical), RN7SL448P (77% identical), RN7SL464P (77% identical), and 700 more.